CXCR1 (C-X-C motif chemokine receptor 1)
Diseases named in the same sentence as CXCR1 in open-access papers (continued):
Sharing a sentence is not in itself a finding about the gene and the disease.
liver cancer (5 papers, 2020 to 2025). An epithelial or non-epithelial malignant neoplasm that arises from the liver. "For example, IL-8 promotes the migration of liver cancer cells through CXCR1 and CXCR2, and targeting CXCR1/2 may be a strategy for treating liver cancer." (PMID 34516330, 2021). "It has been reported that the IL-8 receptors CXCR1 and CXCR2 are highly expressed in HepG2, Huh7, and other liver cancer cells." (PMID 41081508, 2025). "Interleukin-8 promotes cell migration via CXCR1 and CXCR2 in liver cancer." (PMID 33336008, 2020).
metastatic melanoma (5 papers, 2023 to 2025). A melanoma that has spread from its primary site to another anatomic site. "SX-682 (a CXCR1/2 antagonist) in combination with pembrolizumab entered Phase 1 trials in metastatic melanoma (NCT03161431), while a combination of avarixin (CXCR1/2 antagonist) and pembrolizumab is being trialed in advanced/metastatic solid tumors in a Phase 2 study (NCT03473925)." (PMID 37511453, 2023). "In addition, multiple therapeutic approaches targeting neutrophils have emerged, with several reagents entering clinical trials, such as the CXCR1/2 inhibitor SX-682 for metastatic melanoma (NTC03161431), from which OtoNP+ NPC patients might benefit." (PMID 38388556, 2024).
myelofibrosis (5 papers, 2022 to 2026). A partial or complete replacement of the bone marrow stroma by fibrous tissue. "Here, we demonstrate that, in addition to high levels of TGF-β, the megakaryocytes from the bone marrow of the Gata1low mouse model of myelofibrosis express high levels of murine (m)CXCL1, the murine equivalent of hCXCL8, and its receptors CXCR1 and CXCR2." (PMID 35392239, 2022). "Since CXCR1/CXCR2 are also activated by CXCL6 and MIP2, we may not formally exclude that altered levels of these two chemokines are also involved in the development of myelofibrosis in our model and that their levels where normalized by treatment with Reparixin." (PMID 35392239, 2022).
myeloma (5 papers, 2014 to 2025). "We observed that PVR expression was selectively reduced both at level of mRNA and protein upon blockade of CXCR1/2 receptors on myeloma cells as well as by depletion of IL-8 via shRNA in BMSCs." (PMID 32069911, 2020). "The article examines the role of CXCR1, CXCR2, and CXCR3 ligands in tumor biology in multiple myeloma (MM) and monoclonal gammopathy of undetermined significance (MGUS)." (PMID 40940985, 2025). "Certainly we were able to observe that SDF-1, which binds to CXCR4, and CXCL8 (IL-8) which is a ligand for CXCR1/CXCR2, are also significantly elevated in myeloma." (PMID 28389623, 2017).
ovarian tumors (5 papers, 2020 to 2023). "Mounting evidence suggests that G-protein-coupled receptors (GPCRs), such as CXC chemokine receptor 1/2 (CXCR1/2), are the mutual receptors of GROα in human cancers, including ovarian tumors." (PMID 36624516, 2023). "Noticeably, depletion of Cxcr1/2 receptors impeded the oncogenic effects of GROα, preventing intraperitoneal dissemination of ovarian tumors and highlighted the possibility of targeting the miR-141/YAP1/GROα/CXCR1/2 signaling cascade to combat OvCa metastases." (PMID 36624516, 2023). "The expression of CXCR1/2/3/4/7 mRNA in different pathological types of ovarian tumors was significantly different (P < 0.05)." (PMID 33829065, 2021). "Both ex vivo and in vivo, we used a CXCR1/2 inhibitor to sensitize ovarian tumor cells to carboplatin and circumvent the pro-tumoral effects of CA-MSCs." (PMID 31504643, 2020). "CXCR1/2 ligands can also inhibit the immune response against ovarian tumor cells." (PMID 31504643, 2020).
psoriasis (5 papers, 2012 to 2025). An autoimmune condition characterized by red, well-delineated plaques with silvery scales that are usually on the extensor surfaces and scalp. "Moreover, a neutrophil activation signature has been identified in blood in patients with psoriasis, and higher expression of CXCR1 and neutrophil elastase are present in synovial tissue in PsA compared to rheumatoid arthritis." (PMID 37131254, 2023). "We identified five cytokines and receptors that intersected between urticaria, atopic dermatitis, and psoriasis: IL36G, IL20, IL1B, CXCR1, and CXCL1." (PMID 40159643, 2025).
pulmonary fibrosis (5 papers, 2020 to 2025). Chronic progressive interstitial lung disorder characterized by the replacement of the lung tissue by connective tissue, leading to progressive dyspnea, respiratory failure, or right heart failure. "A further cytokine mediator of lung fibrosis is IL‐8 which stimulates macrophages to migrate to fibroblastic foci via CXCR1/2 receptors." (PMID 39807767, 2025). "In mice, antagonism of Cxcr1 and Cxcr2 reduces pulmonary fibrosis, acting on endothelial cells, neutrophils, and fibroblasts, and mediating neutrophilic lung inflammation, angiogenesis, and fibrogenesis." (PMID 39768150, 2024). "Reparixin, an inhibitor of IL-8 receptors CXCR1/2, blocked PM-induced neutrophil accumulation and ameliorated the aggravation of pulmonary fibrosis induced by PM." (PMID 33706759, 2021). "Reparixin, an inhibitor of IL-8 receptor such as CXCR1/2, inhibits neutrophil influx, fibrogenic cytokine, and decreases pulmonary fibrosis by blocking CXCR2." (PMID 33706759, 2021). "The severity of pulmonary fibrosis and the expression of ACE2 and TMPRSS2 caused by PM exposure were blocked by deletion of KC, a murine homologue of IL-8, or treatment with reparixin, an inhibitor of IL-8 receptors CXCR1/2." (PMID 33706759, 2021). "Similarly, the CXCR1/R2 inhibition exerted by ladarixin, a dual allosteric blocker of CXCR1/R2 structurally similar to Reparixin, has been shown to reduce neutrophil infiltration and collagen deposition in the bleomycin-induced mouse model of pulmonary fibrosis." (PMID 35392239, 2022). "Indeed, we have previously evaluated the role of CXCR1 and CXCR2 in the context of experimental pulmonary fibrosis." (PMID 33123138, 2020). "Therefore, the CXCR1 and CXCR2 activation may contribute to the pulmonary fibrosis in human and mouse models." (PMID 33123138, 2020).
thyroid cancer (5 papers, 2018 to 2025). "Previous studies have shown that the CXCR1/2 inhibitor Reparixin affects the viability of various thyroid cancer cells." (PMID 34790698, 2021). "It was hypothesized that CXCL8 would exert its active role in thyroid cancer progression by paracrine binding to CXCR1 and CXCR2 expressed on the surface of PTC cells." (PMID 29977225, 2018).
type 2 diabetes (5 papers, 2020 to 2024). "In addition, CXCR1 expression was higher in neutrophils from type 2 diabetes patients than in those from healthy controls (P = 0.022)." (PMID 32377527, 2020). "We further measured and compared the gene expression of CXCR1, SELL, ITGA4, ITGAM, NCF4, ARHGAP3, and CLDN15 in neutrophils from 5 type 2 diabetes patients within 1 year from diagnosis and 5 age- and sex-matched healthy control subjects." (PMID 33391182, 2020). "In accordance with this finding, our RNA-seq analysis revealed that the CXCR1 and CXCR2 genes were significantly upregulated in patients with type 2 diabetes compared with healthy controls." (PMID 32377527, 2020). "Furthermore, qPCR of genes related to neutrophil activation revealed that the expression of SELL, SELP, CXCR1, and S100A8 was significantly increased in neutrophils from type 2 diabetes patients compared with that in neutrophils from controls." (PMID 32377527, 2020).
acute lung injury (4 papers, 2021 to 2025). A condition of lung damage that is characterized by bilateral pulmonary infiltrates (pulmonary edema) rich in neutrophils, and in the absence of clinical heart failure. "Reparixin is an allosteric inhibitor of CXCR1 and CXCR2 that has been shown to inhibit neutrophil trafficking during ischemia-reperfusion injury and acid-induced acute lung injury." (PMID 38352492, 2024).
head and neck cancer (4 papers, 2017 to 2023). A primary or metastatic malignant neoplasm affecting the head and neck. "Another strategy for eliminating NK cell-suppressive activity of MDSCs is based on inhibiting MDSC trafficking with SX-682, a CXCR1/2 inhibitor; this can be used to enhance NK cell immunotherapy in head and neck cancer models." (PMID 36980527, 2023). "Of importance, the pattern of expression was different from patient E9, the nCounter analysis also identified OAS2 as well as another gene CXCR1, showing an increased expression in the head and neck cancer patient N5 at 5 weeks." (PMID 28443095, 2017).
influenza (4 papers, 2017 to 2021). An acute viral infection of the respiratory tract, occurring in isolated cases, in epidemics, or in pandemics; it is caused by serologically different strains of viruses (influenzaviruses) designated A, B, and C, has a 3-day incubation period, and usually lasts for 3 to 10 days. "Altogether, inhibition of CXCR1/2 may be a valid therapeutic strategy for treating lung infections caused by these pathogens, especially controlling secondary bacterial infection after influenza." (PMID 29326698, 2017). "We investigated the role of CXCR1/2 during influenza, pneumococcal, and post-influenza pneumococcal infections." (PMID 29326698, 2017). "This study investigated the role of CXCR1/2 during influenza and pneumococcal infections." (PMID 29326698, 2017). "Once CXCR1/2 antagonism, given before or 6 h after infection, did not decrease the ability of the murine host to deal with either influenza or streptococcal proliferation, we wondered if it would provide a therapeutic benefit to mice undergoing a secondary pneumococcal pneumonia after influenza." (PMID 29326698, 2017). "Lung-recruited neutrophils induced CCR1, CCR2, CCR3, CCR5, CXCR1, CXCR3, CXCR4, which were absent or marginally induced in peripheral blood neutrophils from influenza-infected mice." (PMID 31041196, 2019).
ischemia (4 papers, 2010 to 2023). A hypoperfusion of the BLOOD through an organ or tissue caused by a PATHOLOGIC CONSTRICTION or obstruction of its BLOOD VESSELS, or an absence of BLOOD CIRCULATION. "For the first time, we reported that neuronal CXCR1 mediates neuronal apoptotic cell death in ischemia." (PMID 29323156, 2018). "In this paper, we describe for the first time that neuronal CXCR1 mediates neuronal apoptotic cell death in ischemia." (PMID 29323156, 2018). "Using oxygen-glucose deprivation (OGD) as an in vitro ischemia model, we found that cultured hippocampal neurons under ischemia expressed higher CXCR1 than untreated ones." (PMID 29323156, 2018). "Indeed, a neutralizing anti-IL-8 antibody has significantly reduced ischemia-induced brain damage, further suggesting that inhibition of IL-8 binding to its receptor CXCR1 is another potential target for inhibiting the IL-8 effects, and the decreased CXCR1 expression may play a neuroprotective role." (PMID 20505763, 2010). "It exerts its effects on neutrophils via two different cell surface receptors initially named as CXCR1 and CXCR2, mediating and regulating leukocyte recruitment and activation at sites of inflammation, followed by ischemia, promoting leakage, and neovascularization." (PMID 36845092, 2023). "CXCR1 is a G-protein-coupled receptor activated by the pro-inflammatory chemokine, interleukin-8 (IL-8 or CXCL8), that is up-regulated under acute inflammatory conditions, e.g. after ischemia in the adult rabbit brain." (PMID 20505763, 2010).
liver fibrosis (4 papers, 2011 to 2024). "However, in vitro experiments characterized CXCR1+ macrophages as polarized towards the alternatively activated M2 macrophage phenotype, which is believed to act pro-fibrogenic in hepatic fibrosis." (PMID 21731723, 2011). "The study demonstrated that PPARα activation attenuated liver fibrosis by reducing the expression of pro-inflammatory cytokines and chemokines, including CXCR1 and CXCR2, thus highlighting the potential link between PPARα and CXCR1/2 in liver inflammation and fibrosis." (PMID 39627194, 2024).
lung disease (4 papers, 2011 to 2025). "In the current study, we find that reparixin attenuates key inflammatory phenotypes in our preclinical mouse model of A-T lung disease, thereby indicating that antagonism of CXCR1/CXCR2 may represent an effective therapeutic strategy for this frequent cause of death in A-T patients." (PMID 33608602, 2021). "Thus, our findings indicate that targeted inhibition of CXCR1/CXCR2 attenuates pulmonary phenotypes caused by ATM-deficiency and suggest that this treatment approach represents a viable therapeutic strategy for A-T lung disease." (PMID 33608602, 2021). "In this scenario, several pharmaceutical companies have drawn their attention to identify CXCR1 and CXCR2 chemokine receptors antagonists to treat pulmonary diseases." (PMID 33123138, 2020).
lymph node metastasis (4 papers, 2019 to 2022). "On the other hand, positive CXCR-1 expression has been correlated with lymph node metastasis and poor survival of patients with PDAC, which was attributed to the role of the IL-8/CXCR-1 axis in the regulation of panCSCs." (PMID 31108941, 2019). "Comparative analysis of the CXC chemokine/receptor genes revealed significantly higher expression levels of genes encoding ELR+ CXC chemokines/receptors (CXCL1, CXCL3, CXCL6, CXCR1, and CXCR2) in bone metastases relative to lymph node metastases." (PMID 33195424, 2020).
urinary tract infection (4 papers, 2010 to 2024). "Innate immunity of which Toll-like receptor (TLR) 4 and CXCR1 are key elements plays a central role in the development of urinary tract infection (UTI)." (PMID 21151974, 2010). "While luminal IL-8 could aid neutrophil transmigration across the epithelium as demonstrated in urinary tract infections, autocrine epithelial signaling via apically expressed IL-8 receptors (CXCR1) has also been suggested." (PMID 27446815, 2016). "Besides, CXCR1/CXCR2-knockout mice showed a deficiency in neutrophil migration and bacterial clearance in a urinary tract infection model, and decline in CXCR1/CXCR2 expression may worsen outcome of infections due to impaired neutrophil recruitment." (PMID 22152684, 2011).
uveal melanoma (4 papers, 2007 to 2022). A melanoma derived from melanocytes of the uveal tract. "Our data showed that LDX-mediated inhibition of CXCR1/2 abrogated motility and induced apoptosis in cultured cutaneous and uveal melanoma cells and xenografts independently of the molecular defects associated with the malignant phenotype." (PMID 28129639, 2017). "All 5 human uveal melanoma cell line cytospins stained positive for CXCL1, CXCL8, and their receptors CXCR2 and CXCR1 respectively." (PMID 17261188, 2007). "Importantly, at a dose of 2.5 μmol/L, C29 did not affect the proliferation/survival of uveal melanoma cells (Mel202), which is consistent with a low level of expression of CXCR1/2 in this tumor type." (PMID 31410218, 2019).
acute respiratory distress syndrome (3 papers, 2021 to 2023). Progressive and life-threatening pulmonary distress in the absence of an underlying pulmonary condition, usually following major trauma or surgery. "Notably, blocking IL-8–like signaling through CXCR-1/-2 decreased disease severity in our murine model of SARS-CoV-2–associated acute respiratory distress syndrome (ARDS)." (PMID 34403366, 2021). "However, the role of chemokine receptor CXCR1 in inflammation-inducing experimental autoimmune encephalomyelitis (EAE) and acute respiratory distress syndrome (ARDS) remains largely enigmatic." (PMID 37709757, 2023). "These signaling molecules act on the CXCR1 and CXCR2 receptor, as well as regulate the expression of cytokines from the interleukin family, central to the pathogenesis of fibrotic and inflammatory lung diseases such as IPF and acute respiratory distress syndrome." (PMID 37266432, 2023).
AIDS (3 papers, 2019 to 2025). A syndrome resulting from the acquired deficiency of cellular immunity caused by the human immunodeficiency virus (HIV). "This difference may be related to the unique immune microenvironment of HIV infection, and IL-8 may recruit activated lymphocytes through CXCR1/CXCR2 signaling in advanced AIDS patients." (PMID 41425969, 2025). "p17 matrix protein released by HIV+ cells interacts with leukocytes heparan sulfate proteoglycans (HSPGs), CXCR1 and CXCR2 exerting different cytokine-like activities that contribute to AIDS pathogenesis." (PMID 31673058, 2019). "Recognizing the interaction of B cell clonogenic vp17s with PAR-1, CXCR1, and CXCR2 as key events in sustaining lymphoma growth and dissemination prompts us to study whether the AT20-KLH therapeutic vaccine may represent a promising strategy for fighting AIDS-related lymphomas." (PMID 39066211, 2024).
atopic dermatitis (3 papers, 2021 to 2025). "In a phase 2 clinical trial of etokimab (anti-IL-33 mAb), atopic dermatitis patients had significantly reduced neutrophil migration in a CXCR1 dependent manner." (PMID 34266437, 2021).
Autoimmunity (3 papers, 2021 to 2025). The occurrence of an immune reaction against the organism's own cells or tissues. "CXCL8-dependent neutrophil chemotaxis to the pancreas precedes autoimmunity, and CXCR1/2 blockade mitigates insulitis and T1D development in preclinical models." (PMID 40718478, 2025). "We showed that CXCR1 strengthened the pro-inflammation cytokines production of DCs and further accelerated inflammation and autoimmunity disease progression via a positive feedback loop of CXCL5/CXCR1/HIF-1α." (PMID 37709757, 2023). "Further investigation is therefore warranted to understand how CXCR1 contributes to disease progression during inflammation and autoimmunity." (PMID 37709757, 2023). "Therefore, this study reveals the role and mechanism of CXCR1 in regulating DCs mediating inflammation and autoimmunity." (PMID 37709757, 2023).
bladder cancer (3 papers, 2015 to 2017). "Thus, we included TGFBR, which is connected to SMADs, and the chemokine (C-X-C motif) receptor 1 (CXCR1) connected to ZEB1 and SNAI1 in the bladder cancer model." (PMID 28775339, 2017).
cholestatic cirrhosis (3 papers, 2011 to 2023). "In non-cholestatic cirrhosis, increased IL-8 and CXCR1 levels were associated with hepatic macrophage accumulation." (PMID 21731723, 2011).
clear cell renal carcinoma (3 papers, 2019 to 2023). A malignant epithelial neoplasm of the kidney characterized by the presence of lipid-containing clear cells within a vascular network. "CXCL 8/CXCR1-2 promotes cancer progression in various cancers, while CXCL 2/CXCR1 facilitates renal clear cell carcinoma." (PMID 37540227, 2023).
liver cirrhosis (3 papers, 2011 to 2017). "Then, considering the key role of the HSC cells in liver cirrhosis and hepatocarcinogenesis, the CXCR1 and CXCR2 axes were studied in MSC migration to LX-2 CM." (PMID 29113298, 2017). "In patients with liver cirrhosis, monocytic CXCR1 expression was significantly upregulated compared to healthy controls." (PMID 21731723, 2011). "Our study suggests a novel role of IL-8 for recruitment and activation of hepatic macrophages via CXCR1 in human liver cirrhosis." (PMID 21731723, 2011). "Furthermore, these findings paralleled the intrahepatic expression patterns of up-regulated CXCR1, but not CXCR2, in patients with liver cirrhosis." (PMID 21731723, 2011).
lymphoma (3 papers, 2022 to 2024). A malignant (clonal) proliferation of B- lymphocytes or T- lymphocytes which involves the lymph nodes, bone marrow and/or extranodal sites. "The chemokine receptor expression profiles of de novo DLBCL and tFL substantially differed from those of GC-B, with at least 5-fold higher expression of 15 out of the 18 investigated chemokine receptors (CCR1–CCR9, CXCR1, CXCR2, CXCR6, CXCR7, CX3CR1 and XCR1) in these lymphoma subtypes." (PMID 35887224, 2022).